ITGAV (integrin subunit alpha V)
Diseases named in the same sentence as ITGAV in open-access papers (continued):
Sharing a sentence is not in itself a finding about the gene and the disease.
cancer (122 papers, 2005 to 2026). A tumor composed of atypical neoplastic, often pleomorphic cells that invade other tissues. "ITGB3 forms an αvβ3 heterodimer with ITGAV, which has been implicated in cancer cell adhesion, migration, and invasion." (PMID 40662366, 2025). "Further survival analysis revealed that overexpression of ITGAV was associated with shorter OS in most cancer types, except for KIRC, where higher ITGAV expression was correlated with longer survival." (PMID 40775249, 2025). "Altogether, our findings demonstrate that cSCC relapse is associated with an increased presence of ITGAV+ cancer cells in primary tumors." (PMID 39075581, 2024). "ITGAV expression serves as a risk factor for patient prognosis and has distinct effects on patients with some cancers." (PMID 35927660, 2022). "That is, ITGAV expression consistently played risk roles in all nine cancers, indicating the risk factor of ITGAV for the overall survival of cancer patients." (PMID 35927660, 2022). "The protein product encoded by ITGAV is a subunit of integrins (the other is the β subunit), and thus participates in cancer development." (PMID 35927660, 2022). "Data from several studies suggest that ITGAV is highly expressed in several cancers and demonstrates risk roles in the proliferation and migration of cancer cells." (PMID 35927660, 2022). "Among the 30 significantly differentially expressed wound-healing-associated genes in MPM, ITGAV was identified as a predictor of overall survival in patients suffering from this type of cancer." (PMID 31212858, 2019). "AKR1B1 and ITGAV have been associated with drug resistance associated EMT in cancer." (PMID 37174052, 2023). "ITGAV may serve as a potential marker for cancer prognosis and identification and may be associated with immunity." (PMID 35927660, 2022). "Moreover, other evidence suggests that genes in this cluster, such as the integrin gene ITGAV, were associated with higher progression and spread of various cancers via perineural invasion." (PMID 34121340, 2021). "Integrin subunit alpha V (ITGAV), a member of the integrin family, has been found to be associated with cell differentiation and metastasis and can serve as a prognostic biomarker for a variety of cancers." (PMID 32336950, 2020). "Finally, regarding the key function of angiogenesis in others diseases, and in particular in cancers, it would be interesting to test the ITGAV rs3738919-C allele in these phenotypes." (PMID 17615072, 2007). "In this study, the expression of MYH7 was up-regulated in the liver tissues of mice treated with ustilaginoidin D, indicating that mice treated with ustilaginoidin D have a risk of heart disease, and the down-regulation of ITGAV may be closely related to cancer markers." (PMID 40423332, 2025). "We further investigated whether ITGAV or TIMP-1 was associated with cancer stemness." (PMID 30486830, 2018). "To further explore the potential of ITGAV in pan-cancer therapy, we evaluated its ability to bind several drugs via databases such as DSigDB, PubChem, and PDB." (PMID 40775249, 2025). "In conclusion, our findings suggest that ITGAV can be utilized as an independent prognostic factor for a number of cancers and that its expression level predicts similar results across malignant tumors." (PMID 40775249, 2025). "Overall, these results highlight the potential of ITGAV as an important factor influencing the immune microenvironment and its role in cancer progression." (PMID 40775249, 2025). "Further analysis of ligand-receptor pairs revealed that VTN-(ITGAV + ITGB5), SEMA4D-PLXNB2, GAS6-TYRO3, and FN1-(ITGA3 + ITGB1) were more prevalent in high-risk cancer cells." (PMID 41034991, 2025). "To explore the relationships between ITGAV expression and clinicopathological characteristics, we analyzed data from various cancer types." (PMID 40775249, 2025). "Our analysis revealed significant correlations between ITGAV expression and immune cell infiltration across various cancer types." (PMID 40775249, 2025).
cancer (continued). "In this study, we conducted the first comprehensive pan-cancer analysis of ITGAV expression and its significance via data from the TCGA, GTEX, CCLE, and THPA databases." (PMID 40775249, 2025). "At the tissue level, analyses from the TIMER and TCGA databases revealed that ITGAV was significantly upregulated in a range of cancers, including CHOL, ESCA, HNSC, LIHC, LUAD, LUSC, STAD and THCA." (PMID 40775249, 2025). "Unlike prior studies limited to expression profiling in isolated cancer contexts, our multi-dimensional approach aims to provide an integrative understanding of ITGAV’s biological and immunological roles across cancer types." (PMID 40775249, 2025). "This analysis has significantly advanced our understanding of the ITGAV signature across various cancers, suggesting promising prospects for the development of targeted inhibitors and immunotherapeutic strategies against ITGAV." (PMID 40775249, 2025). "Our findings demonstrate that ITGAV is a promising biomarker for diagnosis, prognosis, and immunotherapy prediction across cancers." (PMID 40775249, 2025). "This study establishes a robust connection between ITGAV expression and immune cell infiltration across cancers such as COAD, LIHC, PRAD, and STAD, underscoring its pivotal role in modulating the TME." (PMID 40775249, 2025). "This enrichment of hybrid/mesenchymal cancer cells in Rel-PT correlated with a higher percentage of ITGAV+ cancer cells in Rel-PT than in NR-PT samples." (PMID 39075581, 2024). "To test the plastic behavior of epithelial ITGAV+ cancer cells, we engrafted EpCAM+ITGAV+ and EpCAM+ITGAV− cancer cells isolated from mixed cSCCs into immunocompetent syngeneic mice." (PMID 39075581, 2024). "ITGAV is also one of the TGFβ-regulated genes, as we observed in the different cancer cell lines by western blot, immunofluorescence, and RNA-seq." (PMID 39304722, 2024). "In contrast to previous studies that focused on ITGAV expression in mesenchymal EpCAM− cancer cells, our data show an increased ITGAV expression within epithelial EpCAM+ cancer cells that correlates with the emergence of epithelial plastic cancer cells." (PMID 39075581, 2024). "EpCAM+ITGAV+ cancer cells gave rise to MD/PD-SCCs containing a higher percentage of mesenchymal EpCAMneg and ITGAV+ cancer cells than EpCAM+ITGAV−-derived tumors." (PMID 39075581, 2024). "Following this, we investigated the mRNA expression levels of NPC2 and ITGAV in 33 human cancers and matched normal tissues and healthy individuals." (PMID 39690926, 2024). "We evaluated the Human Protein Atlas dataset and identified NPC Intracellular Cholesterol Transporter 2 (NPC2) and Integrin Subunit Alpha V (ITGAV) as probable poor predictive genes for these cancers." (PMID 39690926, 2024). "Most of the ITGAV+ cancer cells in NR-PT expressed Vim, indicating that ITGAV identifies the small Vim+ cancer cell population of these tumors." (PMID 39075581, 2024). "Flow cytometry analyses showed that the percentage of ITGAV+ and ITGB3+ cancer cells was significantly higher in mixed compared with epithelial cSCCs, and that most cancer cells in mesenchymal cSCCs were ITGAV+ and ITGB3+." (PMID 39075581, 2024). "We observed a significant increase in the frequency of ITGAV+ cancer cells in mixed cSCCs, and an even higher level in mesenchymal cSCCs." (PMID 39075581, 2024). "We observed that IGF1R inhibition reduces ITGAV expression in cancer cells, accordingly with the EMP reduction of these cells." (PMID 39075581, 2024). "We further confirmed that TGFβ-induced THBS1 interacts with integrin receptor ITGAV, facilitating the migration and invasion of cancer cells in both in vitro and in vivo models." (PMID 39304722, 2024). "We compared the expression of Ecad, Vim, and ITGAV in cancer cells of primary tumors (Met-PT) and in their respective metastases (Met-M)." (PMID 39075581, 2024). "Previous studies also indicated that significant upregulation of ITGAV correlated with the metastatic potential of cancer cells." (PMID 38534932, 2024).
cancer (continued). "We conduct an in‐depth investigation of how NPC2 and ITGAV are expressed in human cancers and adjacent normal tissues." (PMID 39690926, 2024). "The ITGAV protein (integrin subunit αV) has a reported role in cell migration and metastasis in several cancers." (PMID 39639369, 2024). "Molecular characterization of mouse cSCC cancer cells allowed us to identify ITGAV as a marker of hybrid E/M cancer cells." (PMID 39075581, 2024). "Clinically, we found that ITGAV was overexpressed in multiple cancer types, including those tested in our cell surface proteome CRISPR screens." (PMID 38316881, 2024). "Within this protein family, Integrin αV (ITGAV) has received attention for its important functional role in cancer progression." (PMID 38534932, 2024). "In the current study, ITGAV, which has been involved in increased invasion, proliferation, and self-renewal in many cancers, was investigated for its EMT potential in ccRCC." (PMID 37174052, 2023). "This study provided valuable insights for a better understanding of the pathogenesis mechanism of ITGAV in cancers." (PMID 35927660, 2022). "Another essential protein harboring specific GalNAc-T6 glycosylation sites is the integrin ITGAV, which is often overexpressed in cancers and important for keratinocyte proliferation." (PMID 36270990, 2022). "In summary, the AUC of ROC for all 34 cancers was up to 0.86, suggesting that ITGAV expression has the potential to screen cancers." (PMID 35927660, 2022). "Further, the extensive pan-cancer analysis verified the differential expression of ITGAV and its clinical significance in multiple cancers with tens of thousands of samples." (PMID 35927660, 2022). "Positive associations between ITGAV expression and resting CD4 memory T cells, M1 macrophages, and M2 macrophages were observed in more than ten cancers." (PMID 35927660, 2022). "The finding that ITGAV expression makes it feasible to distinguish multiple cancer tissues from their controls suggests the potential of ITGAV expression in screening cancers." (PMID 35927660, 2022). "ITGAV expression has been shown to positively correlate with the molecular signature of mesenchymal cells and metastasis of cancer cells." (PMID 36463238, 2022). "Further, the extensive pan-cancer analysis verified the differential expression of ITGAV and its clinical significance in multiple cancers." (PMID 35927660, 2022). "In summary, diverse ITGAV expression (mainly upregulated) in multiple cancers, its clinical significance, and its potential molecular mechanisms in dozens of cancers were identified in the study." (PMID 35927660, 2022). "Several studies have shown that ITGAV is frequently upregulated in various types of cancers, including EC, melanoma, lung cancer, and prostate cancer." (PMID 34709754, 2021). "Increasing experimental evidence suggests that integrin adhesion receptors, in particular integrin αv (ITGAV), are important for cancer cell survival, proliferation and migration." (PMID 34709754, 2021). "Integrin alpha V (ITGAV) heterodimers has been known to promote or suppress cancer development in epithelial tissues." (PMID 32982756, 2020). "Integrin αv (ITGAV) heterodimers are known to promote or suppress cancer development in epithelial tissues." (PMID 30486830, 2018). "It has also been reported that ITGAV positive colon cancer cells showed increased cancer stemness and chemoresistance." (PMID 30486830, 2018). "Furthermore, these findings provide a robust foundation for future research into the role of ITGAV in cancer pathogenesis, paving the way for more effective therapeutic interventions." (PMID 40775249, 2025). "Hence, we proceeded to analyze the expression patterns of ITGAV in immune subtypes and molecular subtypes of these cancers using the TISIDB database." (PMID 40018050, 2025).
cancer (continued). "Our results elucidated the importance of ITGAV in the prognostic assessment, early diagnosis, and targeted immunotherapy of digestive system cancers, and revealed its multifaceted role in regulating cancer progression." (PMID 40018050, 2025). "Cancer cells interact with fibronectin via integrins: ITGAV, ITGA5, ITGB1 and ITGB3." (PMID 40636307, 2025). "Furthermore, we performed co-expression analysis across 33 cancer types to explore the relationships between ITGAV expression and immune-related genes." (PMID 40775249, 2025). "Notably, EGFR is a well-known oncogene and a promising therapeutic target in multiple cancers, while ITGAV has recently been identified as a critical contributor to cancer metastasis." (PMID 40133476, 2025). "Another cancer-associated module, the adhesion cluster, shows conceptual similarity to the μ-21-specific corresponding cluster, though only three integrin family proteins (ITGA1, ITGA2, ITGAV) are shared between them." (PMID 41373892, 2025). "ITGAV serves as a potential marker for the prognosis and identification of cancers, including SCLC." (PMID 40423332, 2025). "Interestingly, the percentage of ITGAV+ cancer cells initially increased within the EpCAMlow population of mixed cSCCs, this marker being highly expressed in the mesenchymal cancer cells." (PMID 39075581, 2024). "Overall, our results indicate an essential role of ITGAV/RAC1 signaling in cancer cell maintenance." (PMID 38316881, 2024). "Although the biological basis of ITGAV’s contribution to ccRCC tumorigenesis has not yet been fully elucidated, experiments in other cancers have demonstrated an association with well described ccRCC pathways, such as VEGF-mediated neovascularization." (PMID 39639369, 2024). "Since an increased frequency of hybrid/mesenchymal and ITGAV+ cancer cells was observed in Rel-PT samples, we analyzed whether, after relapse, these tumors were enriched in mesenchymal features associated with poor prognosis." (PMID 39075581, 2024). "It has been demonstrated that ITGAV expression increases in a variety of epithelial tumors despite being practically undetectable in normal tissue, which highlights the possible role of integrin expression during cancer development." (PMID 39690926, 2024). "We noted significantly more ITGAV+ cancer cells in Rel-R compared with Rel-PT samples." (PMID 39075581, 2024). "ITGAV expression was mainly observed in EpCAM− cancer cells in mesenchymal cSCCs." (PMID 39075581, 2024). "Likewise, ITGAV knockdown in epithelial plastic cancer cells also blocks EMP acquisition, generating epithelial tumors." (PMID 39075581, 2024). "Finally, NPC2 and ITGAV's molecular pathways in cancer are complex and need to be validated in fully independent research before being implemented in clinical practice." (PMID 39690926, 2024). "In addition, sh-IGF1R cSCCs showed a significant reduction in the expression of ITGAV and in the percentage of ITGAV+ cancer cells compared with sh-control ones, indicating a loss of plasticity following IGF1R abrogation." (PMID 39075581, 2024). "Likewise, EpCAM+ITGAV+ cancer cells expressed higher levels of the plasticity genes Axl, Tnc, Itgb3, and Vcam1 than EpCAM+ITGAV− cancer cells, indicating that EpCAM+ITGAV+ cancer cells exhibit a hybrid E/M phenotype." (PMID 39075581, 2024). "In contrast, most of the ITGAV+ cancer cells in mixed cSCCs retained EpCAM expression." (PMID 39075581, 2024). "Furthermore, enhanced expression of ITGAV in its dimerized form as αvβ3 plays a pivotal role in the transendothelial migration of several invasive human cancers." (PMID 38534932, 2024). "Interestingly, we show that ITGAV knockdown in EpCAMhigh cancer cells generates epithelial cSCCs as those obtained after IGF1R inhibition, demonstrating the involvement of ITGAV in EMP." (PMID 39075581, 2024).
cancer (continued). "Finally, we validated the potential of ITGAV to identify hybrid/plastic cancer cells by analyzing the expression of ITGAV and EpCAM in epithelial, mixed, and mesenchymal mouse cSCCs through standard clinical methods such as IF." (PMID 39075581, 2024). "As a member of integrin receptor family, ITGAV (integrin subunit α V) is involved in a variety of cell biological processes and overexpressed in various cancers, which may be a potential prognostic factor." (PMID 36388191, 2022). "With regard to differently expressed ITGAV and its clinical significance in SCLC, we attempted to perform a similar exploration in pan-cancer analysis, which could contribute to the understanding and application of ITGAV in cancers." (PMID 35927660, 2022). "ITGAV may play a role in cancers by participating in immunity-related signaling pathways and influencing the infiltration levels of several immune cells." (PMID 35927660, 2022). "However, the role of the hsa_circ_0051040/miR-569/ITGAV axis in other cancers needs to be further investigated." (PMID 36429000, 2022). "ITGAV may play a role in cancers by influencing several immunity-related signaling pathways and immune cells." (PMID 35927660, 2022). "In addition, ITGAV expression was related to the expression of many immune checkpoints in a series of cancers and revealed the immunotherapy potential of ITGAV." (PMID 35927660, 2022). "Differential expression of ITGAV in cancer is common, and its high expression is predominant." (PMID 35927660, 2022). "To test the first hypothesis, we took the gene, ITGAV, which is a potential drug target for cancers, as an example." (PMID 34042953, 2021). "The ITGAV (integrin subunit alpha v) gene encodes integrin αv which activates several signaling pathways including MAPK and mTOR and regulates a wide range of cellular processes in cancer biology." (PMID 33718208, 2021). "Moreover, paradoxically, c-Myc has been reported to constrain cancer metastasis via the transcriptional repression of integrin subunit alpha V (ITGAV) and ITGB3 subunits." (PMID 33435156, 2021). "The ITGAV gene knockout validated antibodies (Cloud Clone Corp.)and antibodies produced by MyBioSource were used for Western blot analysis to examine the level of ITGAV in cell lysate and the possible presence of the ITGAV in the conditioned media (CM) of cancer cells." (PMID 33791193, 2020). "In conclusion, ITGAV protein is found in the CM produced by cancer cells and the urine." (PMID 33791193, 2020). "Additionally, knockdown of ITGAV suppressed cancer stemness with decreased expression of cancer stem cell markers." (PMID 30486830, 2018). "ITGAV was involved in cancer progression and was expressed in many cancer types." (PMID 30486830, 2018). "In addition, IL-32γ expression with NF-κB inhibitor treatment further reduced skin inflammation, epidermal hyperplasia, and cancer cell sphere formation and downregulated expression levels of ITGAV and TIMP-1." (PMID 30486830, 2018). "In this study, miR-92b in murine models of pulmonary metastasis impaired lung retention of circulating cancer cells in the short term and impeded overt metastases formation in the long term; similar results could be observed in ITGAV-silenced 30-D cells." (PMID 26934001, 2016). "The ability of ITGAV to regulate cancer progression and locally activate TGF-β/SMAD EMT-signaling pathways, is likely the result of the two UV-miRNAs miR-25 and miR-192, which can target this gene directly, and are up-regulated in the irradiated melanocytes of healthy persons." (PMID 27149382, 2016). "Previous studies have demonstrated that ITGAV may play a role during progression in a variety of cancers." (PMID 25861644, 2015). "ITGAV (αv integrin) is expressed both in normal urothelium and carcinoma." (PMID 25247809, 2014). "In addition, additional research into the special role of ITGAV in each type of cancer is needed." (PMID 40775249, 2025).